ZNF518A (zinc finger protein 518A)
Description:
Through its association with the EHMT1-EHMT2/G9A and PRC2/EED-EZH2 histone methyltransferase complexes may function in gene silencing, regulating repressive post-translational methylation of histone tails at promoters of target genes.
Synonyms: KIAA0335; ZNF518
Tractability: PROTAC: UniProt records ubiquitination sites on it; ubiquitination databases record sites on it.
Gene: Protein-coding gene on chromosome 10 (96,129,695 to 96,205,288, forward strand). Ensembl gene ENSG00000177853.
Subcellular location: Nucleus
Subcellular location (Human Protein Atlas): Nucleoplasm
Gene Ontology:
Molecular function: DNA-binding transcription factor activity, RNA polymerase II-specific
Biological process: regulation of transcription by RNA polymerase II
Cellular component: nucleus
Genetic constraint (gnomAD): Loss-of-function variants: 47 observed, 107.29 expected, observed/expected ratio (o/e) 0.44, 90% interval 0.35 to 0.56. The upper end of that interval is the gene's LOEUF score, 0.56, which puts it in group 2 of 6, group 1 being the genes least tolerant of losing a copy. Missense variants: 1,793 observed, 1,789.9 expected, observed/expected ratio (o/e) 1, 90% interval 0.96 to 1.04. Synonymous variants: 652 observed, 626.58 expected, observed/expected ratio (o/e) 1.04, 90% interval 0.98 to 1.11.
Homologues: Orthologues: chimpanzee ZNF518A (99% identical), macaque ZNF518A (89% identical), dog ZNF518A (85% identical), pig ZNF518A (84% identical), rabbit ZNF518A (79% identical), guinea pig ZNF518A (76% identical), rat Zfp518a (69% identical), mouse Zfp518a (68% identical), tropical clawed frog znf518a (32% identical), Drosophila melanogaster hb (6% identical), Caenorhabditis elegans Y5F2A.4 (4% identical), Drosophila melanogaster CG12391 (4% identical), and 1 more. Paralogues in human: ZNF518B (16% identical), PEG3 (8% identical), REST (6% identical), ZNF770 (5% identical), ZBTB35 (5% identical), PLAG1 (5% identical), PLAGL2 (5% identical), ZNF274 (4% identical), ZSCAN32 (4% identical), ZSCAN5A (4% identical), PLAGL1 (4% identical), OVOL1 (4% identical), and 17 more.